SLC31A1 (solute carrier family 31 member 1)
Diseases named in the same sentence as SLC31A1 in open-access papers (continued):
Sharing a sentence is not in itself a finding about the gene and the disease.
cancer (69 papers, 2014 to 2025). A tumor composed of atypical neoplastic, often pleomorphic cells that invade other tissues. "SLC31A1 has reportedly as a potential biomarker for cancer therapy and has been associated with chemical resistance in specific cancer types." (PMID 41216190, 2025). "Most studies on the relevance of SLC31A1 variants in cancer chemoresistance have been carried out in patients with NSCLC, a type of cancer treated with platinum derivatives." (PMID 39143954, 2024). "According to the COSMIC database of mutations in cancer, SLC31A1 is mutated in less than 1% of samples, reaching 2.1% in HCC, 2.0% in CCA, and 1.8% in endometrial carcinoma." (PMID 39143954, 2024). "For example, there is evidence that genetic polymorphisms of SLC31A1 are associated with chemotherapy resistance and clinical outcomes in cancer patients." (PMID 36973786, 2023). "Missense and truncating mutations constitute the majority of SLC31A1 mutations in different cancers." (PMID 37853210, 2023). "This thorough analysis of SLC31A1 across different types of cancer gives us a clear and comprehensive insight into its role in causing cancer on a systemic level." (PMID 38001885, 2023). "Previous studies have demonstrated that the expression level of SLC31A1 is associated with the chemoresistance of cancers." (PMID 32207235, 2020). "Interestingly, SLC31A1 showed both risk and protective prognostic associations in different cancers, indicating complex, tissue-specific functions that merit further investigation." (PMID 40601654, 2025). "SLC31A1 is abnormally expressed in various cancers and is associated with cancer progression." (PMID 39315155, 2024). "Furthermore, SLC31A1 expression was strongly associated with overall survival and disease-free survival in several cancers." (PMID 37853210, 2023). "S105Y was the most prevalent point mutation in SLC31A1 in TCGA pan-cancer datasets." (PMID 36973786, 2023). "The inverse association between SLC31A1 expression and patient survival suggests that excessive copper ion uptake may promote cancer progression and increase patient mortality." (PMID 37035162, 2023). "SLC31A1 expression was positively correlated with cancer-associated fibroblasts (CAF) in CESC." (PMID 37853210, 2023). "In addition, SLC31A1 expression is significantly associated with NK cells, cancer fibroblasts, and macrophages." (PMID 37853210, 2023). "SLC31A1 gene mutations and methylations were identified in 33 cancers." (PMID 37853210, 2023). "Our findings highlight the context-dependent roles of these genes—particularly FDX1 and SLC31A1—in cancer progression and immune regulation." (PMID 40601654, 2025). "Although this study did not involve therapeutic validation, multiple preclinical studies across cancer types have provided theoretical support for SLC31A1-targeted strategies." (PMID 41216190, 2025). "In this pan-cancer analysis, we systematically profiled the expression and prognostic value of eight well-characterized cuproptosis-related genes—FDX1, LIAS, LIPT1, DLD, DLAT, PDHA1, PDHB, and SLC31A1—across 34 cancer types." (PMID 40601654, 2025). "Research studies have shown that SLC31A1 is abnormally expressed in various cancer types, with significant implications for patient outcomes and survival rates." (PMID 41216190, 2025). "In Cuproptosis-related genes, SPC25 was positively correlated with GCSH, CDKN2A, PDHB, PDHA1, DLAT, DLD, and SLC31A1 of pan-cancer." (PMID 38605119, 2024). "The inhibition of SLC31A1-dependent copper transport leads to anti-cell-death effects in cancer cells." (PMID 38200525, 2024). "SLC31A1, ATP7A, and ATP7B play critical roles in regulating intracellular copper ion concentrations, with SLC31A1 exhibiting elevated expression in various cancer types, thus positioning it as a promising predictive biomarker." (PMID 39619229, 2024). "And SLC31A1 was related to patients’ prognosis as well as immune cell infiltration in several cancers." (PMID 39329964, 2024).
cancer (continued). "On the contrary, the expression of SLC31A1 was higher in 21 cancers, except LAML, KIRC, READ, HNSC, and KIRP." (PMID 38671021, 2024). "Several algorithms, including TIMER, XCELL, QUANTISEQ, CIBERSORT, CIBERSORT-ABS, EPIC, and TIDE, have been employed to investigate the relationship between SLC31A1 and immune cell infiltration in pan-cancer using TIMER 2.05." (PMID 37853210, 2023). "In this study, we analyzed SLC31A1 across human cancer types to gain a better understanding of SLC31A1's role in cancer development." (PMID 38001885, 2023). "Amongst nine cancer types, the expression of SLC31A1 was significantly different between tumors and normal tissues." (PMID 38001885, 2023). "Our study thus warrants further experimental and clinical studies to understand the function of SLC31A1 and its potential practical applications in cancer therapy and prognosis prediction." (PMID 36973786, 2023). "We searched through the gepia database and analyzed for survival curves between the expression levels of the copper ion transporter SLC31A1 and cancer patient survival." (PMID 37035162, 2023). "To investigate the variation of SLC31A1 in cancer malignancies, we utilised the cBioPortal10 platform to analyse mutations in TCGA datasets." (PMID 37853210, 2023). "While several studies have explored the role of CRGs in various cancers, the extent of research on the SLC31A1 gene is limited." (PMID 37610668, 2023). "While assessing the relationship between SLC31A1 and these genes, we discovered that CYB561, URF4, and EML5 were significantly correlated with SLC31A1 expression in the preponderance of cancers." (PMID 37853210, 2023). "Given the importance of SLC31A1 in copper homeostasis, it is necessary to investigate its specific roles of SLC31A1 in various cancers." (PMID 37853210, 2023). "Our pan-cancer analysis demonstrates that the cuproptosis-regulatory gene SLC31A1 is dysregulated in various cancers with its expression and genetic alteration associated with clinical outcomes in patients with these tumors." (PMID 36973786, 2023). "Using comprehensive bioinformatics analysis, we evaluated SLC31A1 expression, prognosis, DNA promoter methylation, gene variations, and immune cell infiltration at the pan-cancer level." (PMID 37853210, 2023). "We used multiple methods common in the field of bioinformatics to investigate the molecular mechanisms of SLC31A1 and provide comprehensive pan-cancer genomics and clinical prognoses." (PMID 37853210, 2023). "Using TIMER2.05, we first observed the expression of SLC31A1 in normal and malignant cancer tissues." (PMID 37853210, 2023). "Such correlation with macrophage infiltration was in line with the high expression level of SLC31A1 in macrophages in single-cell RNA-Seq data, emphasizing the importance of SLC31A1 and the related cuproptosis in the cancer-related immune process." (PMID 36973786, 2023). "The top cancer type associated with SNV of copper cell death genes was BRCA, which had significance in the correlation between SNV of LIAS and SLC31A1 and overall survival." (PMID 36276096, 2022). "A growing body of evidence suggests that SLC31A1 is responsible for the majority of the active transport of platinum drugs in cancer cells." (PMID 32207235, 2020). "Abnormal expression of SLC31A1 in cancer cells affects the sensitivity of cells to platinum drugs and even directly leads to chemoresistance of cancer cells." (PMID 32207235, 2020). "SLC31A1 has been paid close attention on cisplatin uptake in the past years, whereas its role in cancer development has not been fully understood." (PMID 30706544, 2019). "The SLC31A1 gene, also known as copper transporter protein 1, has a high affinity for copper transport in individual cells and is a key gene for copper ion transport, which is used in the study of cancer-related therapies." (PMID 40337173, 2025). "The level of SLC31A1 also has differences among different stages in cancers GBMLGG, and KIRP." (PMID 40601654, 2025).
cancer (continued). "By increasing SLC31A1 expression on the cell membrane, the uptake of copper ions by cancer cells is enhanced, promoting copper-induced cytotoxicity, or “copper poisoning,” which ultimately exerts an anti-cancer effect." (PMID 39702350, 2024). "Studies also suggest that methylation of the SLC31A1 promoter may influence tumor transcription, contributing to cancer progression." (PMID 39702350, 2024). "The molecular mechanism of SLC31A1 in cancers remains to be elucidated." (PMID 36973786, 2023). "Our results suggested that SLC31A1 may play a key role in cancer by influencing metabolic and Cu-related processes." (PMID 36973786, 2023). "Additionally, immune infiltration analysis and gene enrichment analysis provide new insight into potential mechanisms related to SLC31A1 in cancers." (PMID 36973786, 2023). "Based on these, SLC31A1 has been found to act as an oncogene in the progression of numerous cancers and may serve as a useful predictor of cancer prognosis." (PMID 36973786, 2023). "Besides, we noticed that SLC31A1 had been studied in different cancers and strongly correlated with poor prognosis." (PMID 37610668, 2023). "This correlation may provide a potential mechanism for developing novel cancer therapies through inhibition SLC31A1 expression or removal of large amounts of copper ions in tumor tissues." (PMID 37035162, 2023). "Our results indicated that SLC31A1 might contribute to changes in the immune microenvironment in cancer tissues." (PMID 36973786, 2023). "SLC31A1 has recently been proposed as a biomarker for cancer therapy and could play a role in chemoresistance in a few types of cancers." (PMID 36973786, 2023). "To determine whether SLC31A1 plays a role in human cancers, we first examined the expression level of SLC31A1 in the TCGA database." (PMID 37275369, 2023). "Pan-cancer expression profiles of SLC31A1 were also provided." (PMID 35996075, 2022). "Results from the pan-cancer expression analysis of SLC31A1 were demonstrated." (PMID 35996075, 2022). "Interestingly, blockage of copper absorption by targeting the copper transporter 1 (SLC31A1) or usage of copper chelator tetrathiomolybdate (TM) inhibited proliferation of cancer cells and induced a dormancy-like arrest state." (PMID 33816262, 2021). "However, for patients with high SLC31A1 expression, this phenomenon can be exploited to design copper-loaded nano-drugs for treatment, because cancer cells absorb such drugs significantly more easily than normal cells, which can improve cancer treatment by activating cuproptosis." (PMID 39273650, 2024). "SLC31A1 may be a potential key biomarker and therapeutic target in cancers." (PMID 36973786, 2023). "In addition, we acquired the top 100 SLC31A1 co-expressed genes in pan-cancer using GEPIA2.0." (PMID 37853210, 2023). "However, various SLC31A1 properties in pan-cancer profiles remain unknown." (PMID 37853210, 2023). "And we found that MTF1 expression had a positive correlation with the expression levels of SLC31A1 (R = 0.17, p < 0.001), SLC11A2 (R = 0.33, p < 0.001) in pan-cancer." (PMID 37380924, 2023). "In the stemness analysis, STAD was the most striking cancer type, which was positively correlated with the expression of ATP7B, SLC31A1, FDX1, and DLAT." (PMID 36276096, 2022). "In particular, a correlated upregulation of SLC31A1, SCO1, and COX11 mRNA has been observed in cancer cells in vivo and in culture conditions." (PMID 27516958, 2016). "Second, while prior studies have explored cuproptosis-related genes across cancers, our work emphasizes immune correlation and identifies distinctive gene-immune interactions—particularly involving FDX1 and SLC31A1—which were underreported in previous literature." (PMID 40601654, 2025). "A deep analysis based on TCGA and tissue microarrays showed a strong correlation between the expression of SLC31A1 and PD-L1 in many cancers but not in normal tissues." (PMID 37275369, 2023).
cancer (continued). "To date, however, there is no comprehensive pan-cancer study of the function and clinical significance of SLC31A1." (PMID 36973786, 2023). "Moreover, the heatmap confirmed the positive relationship between MTF1 and SLC31A1 and SLC11A2 in almost all cancer types." (PMID 37380924, 2023). "On the contrary, KIRCs were found to potentially have a lower copper cell death in cancer tissue because their anti-cuproptosis gene ATP7B was upregulated with pro-copper metabolism-related cell death genes SLC31A1, FDX1, DLAT, and LIAS downregulated in cancer tissues." (PMID 36276096, 2022). "Thus, our findings that the genetic interaction between SLC31A1 and ABCG2 polymorphisms was associated with clinical outcomes of NSCLC patients receiving platinum-based chemotherapy may have important implications for the pharmacoethnicity of platinating agents in cancer chemotherapy." (PMID 33531973, 2021). "The exon‐level comparison of SLC31A1 transcripts in CRC and normal colonic mucosae suggests the possible existence of novel alternative transcripts and a different quantitative distribution of SLC31A1 alternative transcripts in normal and cancer cells." (PMID 27516958, 2016). "Results showed that the cancer–noncancer protein expression patterns of ATP7B, SLC31A1, DLAT, and LIAS were mostly consistent with the patterns at the mRNA level but that of FDX1 was not." (PMID 36276096, 2022). "In contrast, protein expression of ATP7b (copper transporter ATP7b), mRNA expression of ABCG2 (BCRP, breast cancer resistance protein), ABCC2 (MRP2), and SLC31A1 (hCTR1, human copper transporter 1) did not correlate with survival." (PMID 25275603, 2014).
infection (3 papers, 2011 to 2025). The state of being infected such as from the introduction of a foreign agent such as serum, vaccine, antigenic substance or organism. "Compared to control cells, all KO cell lines (ST3GAL4, SLC31A1, ST6GAL1, and ST3GAL4/ST6GAL1DKO) showed significantly reduced PEDV infection." (PMID 40767522, 2025).
gastrointestinal tumors (1 paper, 2025). "In this context, SLC31A1 appears to be a promising marker for inclusion in expanded pharmacogenetic panels when assessing both toxicity risk and the efficacy of oxaliplatin therapy in gastrointestinal tumors." (PMID 41300713, 2025).
mitochondrial disease (1 paper, 2025). "Therefore, defects in copper transporter receptors due to pathogenic variants in SLC31A1 should be considered in the differential diagnosis of mitochondrial diseases." (PMID 41040850, 2025).
neurodevelopmental disorder (1 paper, 2025). A behavioral and cognitive disorder with onset during the developmental period that involves impaired or aberrant development of intellectual, motor, or social functions. "Recently, bi-allelic mutations in SLC31A1 have been associated with a new neurodevelopmental disorder." (PMID 41040850, 2025).
SLC31A1 also shares sentences with these, for which no sentence is quoted: prostate carcinoma (7 papers); hepatocellular carcinoma (6); glioblastoma (4); adrenocortical carcinoma (3); cholangiocarcinoma (3); esophageal cancer (3); head and neck squamous cell carcinoma (3); Skin Cutaneous Melanoma (3); Wilson disease (3); acute myocardial infarction (2); cervical squamous cell carcinoma (2); gastric cancer (2); germ cell tumor (2); kidney cancer (2); lung squamous cell carcinoma (2); Menkes disease (2); paraganglioma (2); pheochromocytoma (2); prostate adenocarcinoma (2); acute myeloid leukaemia (1); adenocarcinoma (1); bladder cancer (1); Bladder Urothelial Carcinoma (1); bone cancer (1); brain tumor (1); breast invasive carcinoma (1); cardiovascular diseases (1); chronic apical periodontitis (1); clear cell renal cell carcinoma (1); colon adenocarcinoma (1).
A further 40 diseases each share a sentence with SLC31A1 in 1 paper.